CCR7 (C-C motif chemokine receptor 7)
Diseases named in the same sentence as CCR7 in open-access papers (continued):
Sharing a sentence is not in itself a finding about the gene and the disease.
Autoimmunity (continued). "The exocrine organs such as the lacrimal and salivary glands tend to be target organs for autoimmunity in CCR7−/− mice." (PMID 20052419, 2010). "Patrolling Treg cells were detected in the exocrine organs such as lacrimal and salivary glands from normal mice that tend to be targets for autoimmunity while the Treg cells were almost undetectable in the exocrine glands of CCR7−/− mice." (PMID 20052419, 2010). "We thus examined the role of CCR7 signaling in the in vivo function of Treg cells that regulate the development of autoimmunity." (PMID 20052419, 2010). "However, it is unknown whether mutations of CCR7 are linked to autoimmunity in humans." (PMID 17587445, 2007). "During T cell production in the thymus, the absence of CCR7 signaling contributes to autoimmunity manifestation in CCR7-deficient mice." (PMID 35874608, 2022). "It has been observed that the absence of CCR7 is directly associated with the onset of spontaneous autoimmunity." (PMID 35874608, 2022). "Although we assessed changes in naïve and memory CD4+ T cell subsets using CD27 instead of CCR7 as a marker, none of them revealed an association with presence of secondary autoimmunity." (PMID 32539719, 2020). "Together, CCR7-expressing Treg cells within the target tissue may control the organ-specific self-tolerance to prevent autoimmunity in the periphery." (PMID 20052419, 2010). "It was suggested that mature thymocytes exported from the cortex in the absence of CCR7 were potent in causing autoimmunity." (PMID 20052419, 2010). "In addition, no clear correlation has been found between autoimmunity and the observed CCR7 variants." (PMID 17587445, 2007). "Both receptors are required for protection from autoimmunity, with results suggesting that CCR4 and CCR7 promote tolerance against different tissues." (PMID 37266571, 2023). "Although it is still unclear whether the CCR7+Foxp3+ Treg cells in the normal salivary glands are natural naïve Treg cells, the decreased cell number in SS patients suggests that the expression of CCR7 on Treg cells may play a key role in the protection of autoimmunity." (PMID 20052419, 2010). "In order to examine the basis for the decreased number of Treg cells in the target organs of autoimmunity in CCR7−/− mice, Treg cells in lymphoid organs between WT and CCR7−/− mice were compared using flow cytomtric analysis." (PMID 20052419, 2010). "Because low CCR7 and high PD-1 expression have been observed in circulating TFH from patients with autoimmune conditions, we examined the TFH subsets considering the level of expression of these molecules on the surface of CXCR5+CD4+ T cells from CVID patients and N controls." (PMID 27069935, 2016). "CD8 Treg (CD8+CD183+CCR7+CD45RA-) were significantly reduced in the patient as compared to control, which may contribute to autoimmunity in T-LGL." (PMID 26429871, 2015). "Notably, CCR7 has been shown to play a critical role in directing chemotaxis of post-positive selection thymocytes toward the medulla, where CCR7 ligands are expressed, enhancing thymocyte accumulation within the medulla, enforcing negative selection to TRAs, and averting autoimmunity." (PMID 37266571, 2023). "Related to unwanted autoimmune side-effects, lack of CCR7 signaling in TREG hampered central and peripheral tolerance and led to generalized multi-organ autoimmunity." (PMID 34778050, 2021).
gastric cancer (26 papers, 2011 to 2025). A primary or metastatic malignant neoplasm involving the stomach. "High CCR7 expression had been reported to be associated with poor overall survival in gastric cancer." (PMID 37208608, 2023). "Overall, the data supports a role for CCR7 in H. pylori-linked gastritis and gastric cancer progression." (PMID 35203305, 2022). "The pooled hazard ratios indicated a statistically significant risk of a lower 5 year overall survival rate for CCR7+ vs. CCR7− gastric cancers (HR = 0.46, 95% CI 0.31–0.70." (PMID 35203305, 2022). "In this study, a meta-analysis was performed on 15 eligible studies, totaling 1697 patients, to assess the gastric cancer risk of CCR7." (PMID 35203305, 2022). "MiR-let-7a can modulate CCR7 expression and this was also seen in gastric cancers, where high CCR7 expression was associated with reduced levels of miR-let-7a, most likely due to the low expression of Dicer 1 that is required to produce the microRNA." (PMID 35203305, 2022). "A second study reported that CCR7 expression in gastric carcinomas was closely linked to expression of the transcription factor, Snail, which represses E-cadherin, thereby promoting EMT." (PMID 35203305, 2022). "Regarding CC chemokines, CCL7 and CCL21 overexpression is associated with poor prognosis, CCR7 and CCR5 receptors associate with invasion and metastasis in gastric cancer, and lastly CCR7 is associated with EMT." (PMID 32499779, 2020). "CCR7 expression has previously been associated with intrapleural dissemination in non-small cell lung cancer, gastric carcinoma, and so on, implying the relevant function of CCR7 expressing during carcinogenesis in these cancers." (PMID 21548969, 2011). "In this study, we explored whether CCR7 expression in gastric cancer cells and intratumoral FOXP3+ Tregs were associated with clinicopathological factors and could be used as a prognostic indicator." (PMID 24040244, 2013). "Importantly, our results indicated that CCR7 expression in gastric cancer cells was associated with OS by Kaplan-Meier analysis, patients with high CCR7 expression tumors had a significantly shorter survival than those with low CCR7 expression tumors." (PMID 24040244, 2013). "CCR7 expression in gastric cancer cells was associated with the OS rates (log-rank test, P = 0.010<0.05), one-year, two-year and three-year OS rates were 91.4%, 78.5% and 72% for the high CCR7 expression groups, respectively, compared with 100%, 97.5% and 92.4% for the low CCR7 expression groups." (PMID 24040244, 2013). "Patients with high expression levels exhibited poorer OS, suggesting that CCL19/CCR7 can serve as indicators of poor prognosis in patients with gastric cancer." (PMID 39840050, 2024). "In database analyses of chemokines in gastric cancer samples, the expression of CCL19 and CCR7 was significantly higher in gastric cancer samples compared with normal tissues." (PMID 39840050, 2024). "The results also showed that patients with high CCL19 and CCR7 expression had worse overall survival, suggesting that CCL19/CCR7 indicates poor prognosis in gastric cancer." (PMID 37208608, 2023). "Our research came to a similar conclusion that CCL19/CCR7 indicated poor prognosis in gastric cancer." (PMID 37208608, 2023). "Analysis of 876 gastric cancer patients in KMplotter database demonstrated that patients with high CCR7 expression had worse overall survival than those with low CCR7 expression." (PMID 37208608, 2023). "Both CCL19 and CCR7 expression were significantly upregulated in gastric cancer samples compared with that in matched normal samples." (PMID 37208608, 2023). "Other statistically significant end points for CCR7+ vs. CCR7− gastric cancers included deeper tumor invasion, advanced stage, vascular invasion, lymph node metastasis and lymphatic invasion." (PMID 35203305, 2022).
gastric cancer (continued). "In stomach cancer expression of CCR7, early tumor cells were investigated as the most significant component in the determination of lymph node metastasis in cancers." (PMID 35874608, 2022). "CCR7 was expressed in all gastric cancer cell lines and 84% of gastric cancer tissues by RT-PCR and 22.5% by immunohistochemistry." (PMID 35203305, 2022). "In gastric cancer, tumor cell CCR7 expression resulted in an increased Treg population and elevated tumor cell survival." (PMID 35203305, 2022). "CCL19 and CCL21 are chemokines and CCR7 is their receptor in gastric cancer and esophageal squamous cell carcinoma." (PMID 36263088, 2022). "An early study of CCR7 expression in gastric cancer analyzed 10 human gastric cancer cell lines and 43 gastric cancer tissues by RT-PCR and an additional 307 gastric cancer tissues by immunohistochemistry." (PMID 35203305, 2022). "A more recent study concurred that gastric cancer expresses CCR7 at high levels, with ~70% CCR7 expression from 133 patient samples." (PMID 35203305, 2022). "CCR7 expression was linked to the presence of intratumoral FOXP3+ Treg cells, suggesting that the gastric cancer milieu favored tumor survival and CCR7-mediated lymphatic invasion." (PMID 35203305, 2022). "In a small study, four of six gastric carcinoma cell lines expressed CCR7 and were able to migrate in response to CCL21." (PMID 35203305, 2022). "Another study reported lower levels of CCR7 expression in resected gastric carcinoma cells (30/93, 32%), which again correlated with lymph node migration." (PMID 35203305, 2022). "The proliferation, migration, and invasion of stomach cancer cells are inhibited by CCL19 via the CCL19/CCR7/AIM2 pathway." (PMID 34367971, 2021). "In gastric cancer, the high expression of CCR7 and CCL21 can lead to the preferential metastasis of gastric cancer cells to lymphatic vessels." (PMID 33158173, 2020). "In a meta-analysis including 1697 gastric cancer patients, high CCR7 correlated with a worse 5-year overall survival rate." (PMID 28114889, 2017). "In this study, we used immunohistochemistry with tissue microarrays to measure CCR7 expression in tumor specimens from 122 patients with gastric cancer." (PMID 26176983, 2015). "The CCR7 mechanism was predicted based on bioinformatic analysis and verified in gastric cancer cell lines and primary tumor samples." (PMID 26176983, 2015). "Further investigation is recommended to examine the prognostic impact of CCR7 expression and Tregs in gastric cancer." (PMID 24040244, 2013). "The result showed that there was a significantly positive correlation between CCR7 positive score of gastric cancer cells and intratumoral FOXP3+ Treg cell number (r = 0.949, P<0.001)." (PMID 24040244, 2013). "In this study, we investigated the prognostic value of CCR7 expression in gastric cancer cells and intratumoral FOXP3+ Tregs, and the relationship between them in gastric cancer." (PMID 24040244, 2013). "This is, to the best of our knowledge, the first report demonstrating that high CCR7 expression in gastric cancer cells was in parallel with marked infiltration of intratumoral FOXP3+ Tregs in the tumor microenvironment." (PMID 24040244, 2013). "In the present study, it was interesting that either CCR7 expression or intratumoral FOXP3+ Tregs was found to be an independent prognostic factor in gastric cancer." (PMID 24040244, 2013). "We compared CCL19/CCR7 expression in gastric cancer patients in TCGA database." (PMID 37208608, 2023). "Both CCL19 and CCR7 expression were significantly upregulated in gastric cancer tissues." (PMID 37208608, 2023). "We conducted survival analysis of CCL19 and CCR7 in gastric cancer database." (PMID 37208608, 2023). "Survival analysis demonstrated that both CCL19 and CCR7 indicate poor prognosis in gastric cancer." (PMID 37208608, 2023). "Similarly, in gastric cancers, a reduction in miR-let-7a activity led to increased CCR7 expression, gastric cancer progression and metastasis." (PMID 35203305, 2022).
gastric cancer (continued). "In gastric cancers, increased CCR7 led to increased TGF-β1 and EMT." (PMID 35203305, 2022). "Moreover, patients with CCR7+ gastric cancers had a better prognosis than patients with CCR7- gastric cancer." (PMID 35203305, 2022). "Taken together, these results suggest a key role for CCR7 in EMT progression of gastric cancers." (PMID 35203305, 2022). "In the first study, CCR7 expression was limited to the gastric epithelium of all patients tested; however, receptor staining was stronger in H. pylori-infected gastric cells, which included gastric carcinoma." (PMID 35203305, 2022). "A meta-analysis study suggested that high CCR7 expression may lead to poor survival and prognosis in patients with gastric cancer." (PMID 34367971, 2021). "For example, CCL19 inhibited cell proliferation, migration, and invasion in gastric cancer by activating the CCR7/AIM2 signaling pathway, which could be a potential therapeutic approach." (PMID 33344235, 2020). "The prognostic value of CCR7 expression has also been demonstrated in gastric cancer." (PMID 26176983, 2015). "CCR7 positive score of gastric cancer cells and intratumoral FOXP3+ Treg cell number could be represented in the same scatterplot, from the scatterplot, two variables seemed to have a linear trend that could be carried out linear regression analysis." (PMID 24040244, 2013). "High CCR7 expression was detected in 69.9% of 133 gastric cancer samples." (PMID 24040244, 2013). "Further studies will be needed to understand whether blockade of SLC/CCR7 interaction in combination with FOXP3+ Tregs depletion can inhibit the metastasis of gastric cancer cells to lymph nodes, and lead to better treatment outcomes or not." (PMID 24040244, 2013). "Furthermore, multivariate analysis demonstrated that CCR7 expression was an independent prognostic indicator in gastric cancer." (PMID 24040244, 2013). "CCL19/CCR7 may be a potential novel therapeutic target in gastric cancer." (PMID 37208608, 2023). "In addition, the high expression level of CCR7 has been identified in a wide variety of cancer cells, including breast cancer cells, rectal cancer cells, prostate cancer cells, esophageal squamous cell cells, and gastric cancer cells." (PMID 33158173, 2020). "In conclusion, our results demonstrated that both high CCR7 expression in tumor cells and increased intratumoral FOXP3+ Tregs were associated with worse OS in gastric cancer, positively correlated with each other, and could be considered as a co-indicator of clinical prognosis of gastric cancer." (PMID 24040244, 2013). "A research team explored the effect of CCR7 on TGF-β1-induced EMT for the first time, showing that CCR7 acts as a co-stimulator of TGF-β1 in gastric cancer, with NF-κB signaling also playing a role in this process." (PMID 39840050, 2024). "Therefore, both CCL19 and CCR7 may be the potential novel therapeutic targets in gastric cancer." (PMID 37208608, 2023). "Analysis of 122 patients with gastric cancer revealed that EMT in gastric cancers was mediated, at least in part, by CCR7." (PMID 35203305, 2022). "Another study of 82 gastric cancers found that VEGF-C, VEGF-D and CCR7 were present in 88%, 63% and 67% of cases, respectively." (PMID 35203305, 2022). "In gastric cancers, HIF-1α can upregulate CCR7 along with increasing COX-2 production and expression of MMP which are associated with EMT and poor survival." (PMID 35203305, 2022). "CCL19 overexpression significantly inhibited gastric cancer cell proliferation and tumor growth through CCL19/CCR7/AIM2 pathway." (PMID 34544443, 2021). "CCL20/CCR6 induced gastric cancer EMT through the activation of the AKT pathway in response to CrkL; similar results were found with CCL21/CCR7 axis activated JAK2/STAT3 signaling pathways in promoting stemness of OSCC EMT progression." (PMID 34943853, 2021).
gastric cancer (continued). "We conclude that the CCR7 axis mediates TGF-β1-induced EMT via crosstalk with NF-κB signaling, facilitating lymph node metastasis and poorer overall survival in patients with gastric cancer." (PMID 26176983, 2015). "The expression levels of CCR7 and FOXP3 in tissue microarrays of gastric cancer were examined by immunohistochemical analysis." (PMID 24040244, 2013). "CCR7+ tumor cells and FOXP3+ Tregs were assessed by immunohistochemistry in tissue microarrays containing gastric cancer from 133 patients." (PMID 24040244, 2013). "The aim of this study was to investigate the prognostic value of chemokine receptor CCR7 expression and intratumoral FOXP3+ regulatory T cells (Tregs) in gastric cancer." (PMID 24040244, 2013). "Even though the current epidemiological data indicates that CCR7 activation is an undesirable parameter for gastric cancer, results are not unequivocal." (PMID 35203305, 2022). "Furthermore, approximately half of gastric cancers co-expressed VEGF-C and CCR7 and sometimes VEGF-D that strongly predicted lymph node metastasis." (PMID 35203305, 2022). "In addition, CCR7/Snail upregulation led to increased levels of the EMT markers, p-ERK, p-AKT and MMP-9 and sped up the G1/S phases of the cell cycle when the human gastric cancer cell line, MGC803, was incubated with CCL19." (PMID 35203305, 2022). "In tissue microarrays of gastric cancers collected from 133 patients, which have been shown to be a powerful tool for evaluating tumor specimens, we used an immunohistochemical method to examine the expression levels of CCR7 and FOXP3 in gastric cancer tissues." (PMID 24040244, 2013). "Regarding the mechanism of FMNP-labeled MSCs recognizing in vivo gastric cancer cells, we consider that CCL19/CCR7 and CXCL12/CXCR4 axis loops may be involved in this course." (PMID 22709686, 2012). "CCR7 is expressed in gastric epithelial cells of non-inflamed gastric mucosa, H. pylori gastritis, intestinal epithelial chemotaxis, ectopic hyperplasia, and gastric cancer." (PMID 39840050, 2024). "Therefore, CCL19 can activate the CCR7/AIM2 signaling pathway, suggesting that it could be a potential therapeutic method to treating gastric cancer." (PMID 36248785, 2022). "Therefore, our study demonstrated that both high CCR7 expression and increased intratumoral FOXP3+ Tregs could be considered as an indicator of poor prognosis in gastric cancer." (PMID 24040244, 2013). "Then we analysed CCR7, the receptor of chemokine CCL19, in 32 pairs of cancerous and noncancerous tissues from gastric cancer patients in TCGA database." (PMID 37208608, 2023).